MILR1 (mast cell immunoglobulin like receptor 1)
Description:
Immunoglobulin-like receptor which plays an inhibitory role in degranulation of mast cells. Negatively regulates IgE-mediated mast cell activation and suppresses the type I immediate hypersensitivity reaction (By similarity).
Synonyms: MCA-32; C17orf60; MCA32; Allergin-1
Tractability: Antibody: UniProt places it where antibodies can reach, with high confidence; UniProt predicts a signal peptide or a membrane-spanning region; its Gene Ontology location is reachable by antibodies, with medium confidence.
Gene: Protein-coding gene on chromosome 17 (64,449,037 to 64,492,770, forward strand). Ensembl gene ENSG00000271605.
Subcellular location: Cell membrane
Gene Ontology:
Molecular function: protein binding; transmembrane signaling receptor activity
Biological process: cell surface receptor signaling pathway; immune response; mast cell degranulation; negative regulation of mast cell activation
Cellular component: external side of plasma membrane; plasma membrane
Genetic constraint (gnomAD): Loss-of-function variants: 7 observed, 10.74 expected, observed/expected ratio (o/e) 0.65, 90% interval 0.37 to 1.22. The upper end of that interval is the gene's LOEUF score, 1.22, which puts it in group 5 of 6, group 1 being the genes least tolerant of losing a copy. Missense variants: 87 observed, 82.26 expected, observed/expected ratio (o/e) 1.06, 90% interval 0.89 to 1.26. Synonymous variants: 25 observed, 29.52 expected, observed/expected ratio (o/e) 0.85, 90% interval 0.62 to 1.18.
Homologues: Orthologues: chimpanzee MILR1 (97% identical), macaque MILR1 (90% identical), pig MILR1 (66% identical), dog MILR1 (64% identical), rat Milr1 (31% identical), mouse Milr1 (31% identical), zebrafish zgc:154125 (13% identical), zebrafish si:ch1073-66l23.1 (13% identical). Paralogues in human: FCGR1A (18% identical), FCRL3 (18% identical), FCRL4 (17% identical), FCRL5 (17% identical), FCRLB (15% identical), FCGR2B (14% identical), PECAM1 (14% identical), FCGR2A (13% identical), FCGR2C (13% identical), FCRL2 (13% identical), FCRL6 (12% identical), FCRLA (11% identical), and 5 more.
Diseases named in the same sentence as MILR1 in open-access papers:
MILR1 is named in the same sentence as 16 diseases in open-access papers, as found by Europe PMC text mining. Sharing a sentence is not in itself a finding about the gene and the disease. The quoted sentences say what the papers report.
allergic disease (2 papers, 2013 to 2014). An immune response that occurs following re-exposure to an innocuous antigen, and that requires the presence of existing antibodies against that antigen. "Interestingly, top-listed differentially expressed Th17-associated genes S100B, MILR1 and CHI3L1 have been reported to play roles in allergy and asthma." (PMID 24991220, 2014).
breast carcinoma (1 paper, 2025). "Additionally, twenty-one genes were observed to be targeted by variant-containing TCNEs with eQTL data from GTEx and the top three genes (LARS, SURF1, and MILR1) were significantly related to specific genetic variant loci of breast cancer (Storey’s Q<1×10−8)." (PMID 40427520, 2025).
dementia (1 paper, 2024). Loss of intellectual abilities interfering with an individual's social and occupational functions. "The classification performance of seven core DEGs identified in SAH and dementia was evaluated, with ROC curve analysis demonstrating their strong discriminative capabilities, particularly PAPOLA in dementia with an AUC of up to 0.989, followed by DOK3, LONRF3, and MILR1, all exceeding 0.900." (PMID 39726593, 2024).
hemophagocytic lymphohistiocytosis (1 paper, 2025). "They identified MILR1 and FLT3 as pre-infusion biomarkers predictive of severe CRS and noted that CRS may be an IFNγ-driven process with a protein signature overlapping with hemophagocytic lymphohistiocytosis." (PMID 40004863, 2025).
infection (7 papers, 2019 to 2024). The state of being infected such as from the introduction of a foreign agent such as serum, vaccine, antigenic substance or organism. "During infection of apple trees by the fungal pathogen Valsa mali, two genes encoding receptor‐like kinases, MdRLKT1 and MdRLKT2, are targeted by the fungus' sRNA vm‐milR1." (PMID 37438989, 2023). "Using a polyclonal antibody specific to SlyAGO4a, our results suggest that Fol‐milR1 associates with SlyAGO4a to reduce plant immunity, leading to effective infection, which is an AGO1‐associated independent invasion strategy." (PMID 33960431, 2021). "In the apple canker disease pathogen Valsa mali (Vm), Vm-milR1 is complementary to receptor-like kinase mRNAs in its host plant, and Vm-milR1 was shown to be highly upregulated during infection." (PMID 37569766, 2023). "tritici (Pst), the fungal milRNA, Pst-milR1, was found to be an important virulence factor mediating the infection of wheat by the fungus, where it directed silencing of PR2 gene expression." (PMID 37569766, 2023). "We evaluated the ability of a potential sRNA effector, Fol‐milR1, to be transferred from Fol to a tomato host plant during infection." (PMID 33960431, 2021). "Taken together, these results show that B. bassiana markedly reduces bba-milR1 expression during late stages of infection to elaborately avoid induction of CLIPB9, and in this way circumvent the melanization response." (PMID 31541102, 2019). "To confirm that Spz4 can be targeted by bba-milR1 during infection, we further examined the expression levels of Spz4 in mosquitoes after infection with wild-type B. bassiana (WT) and bba-milR1 overexpression strain (milR1-OV)." (PMID 31541102, 2019). "Deletion of the Pst‐milR1 precursor prevents infection of wheat plants by P. striiformis." (PMID 37438989, 2023). "Given the high expression level of bba-milR1 at early stages of infection, we hypothesized that it may play a role in the interaction between fungus and host." (PMID 31541102, 2019). "However, the expression of CLIPB9 was significantly higher and lower in the mosquitoes infected by B. bassiana milR1-OV and the milR1-KO mutant, respectively, than the WT-infected mosquitoes at late stages of infection (84 hpi)." (PMID 31541102, 2019). "Similarly, infection of milR1-OV and milR1-KO resulted in significant increase and decrease in A. stephensi hemolymph PO activity compared with WT at 84 hpi, respectively." (PMID 31541102, 2019). "To confirm whether CLIPB9 is indeed modulated by bba-milR1 during infection, we examined the transcript levels of CLIPB9 in mosquitoes after infection with WT, milR1-OV, and milR1-KO strains." (PMID 31541102, 2019).
neurodegenerative disease (1 paper, 2023). A disorder of the central nervous system characterized by gradual and progressive loss of neural tissue and neurologic function. "Taken together, the role of the Milr1 gene (Allergin-1) in neurodegenerative diseases, especially AD, is sensible." (PMID 37410787, 2023).
tumor (1 paper, 2021). "Besides, the top 30 DEGs included other functional genes, for example, CCL2036 and MILR1, 37 are related to tumor microenvironment and inflammation." (PMID 34185414, 2021).
MILR1 also shares sentences with these, for which no sentence is quoted: mastocytosis (2 papers); Allergy (1); Alzheimer disease (1); anaphylaxis (1); asthma (1); bronchiolitis (1); fungal infection (1); RSV bronchiolitis (1); systemic lupus erythematosus (1).